IVNS1ABP (influenza virus NS1A binding protein)
Description:
Involved in many cell functions, including pre-mRNA splicing, the aryl hydrocarbon receptor (AHR) pathway, F-actin organization and protein ubiquitination. Plays a role in the dynamic organization of the actin skeleton as a stabilizer of actin filaments by association with F-actin through Kelch repeats (By similarity). Protects cells from cell death induced by actin destabilization (By similarity). Functions as modifier of the AHR/Aryl hydrocarbon receptor pathway increasing the concentration of AHR available to activate transcription. In addition, functions as a negative regulator of BCR(KLHL20) E3 ubiquitin ligase complex to prevent ubiquitin-mediated proteolysis of PML and DAPK1, two tumor suppressors. Inhibits pre-mRNA splicing (in vitro). May play a role in mRNA nuclear export. (Microbial infection) Involved in the alternative splicing of influenza A virus M1 mRNA through interaction with HNRNPK, thereby facilitating the generation of viral M2 protein. The BTB and Kelch domains are required for splicing activity. Promotes export of viral M mRNA and RNP via its interaction with mRNA export factor ALYREF.
Synonyms: NS1-BP; ARA3; FLARA3; KIAA0850; KLHL39; NS1BP; HSPC068; NS-1; ND1; IMD70
Tractability: Small molecule: it belongs to a druggable protein family. PROTAC: ubiquitination databases record sites on it; its protein half-life has been measured.
Gene: Protein-coding gene on chromosome 1 (185,292,931 to 185,317,780, reverse strand). Ensembl gene ENSG00000116679.
Subcellular location: Cytoplasm; Cytoplasm, cytoskeleton; Nucleus, nucleoplasm
Subcellular location (Human Protein Atlas): Cytosol
Gene Ontology:
Molecular function: protein binding; ubiquitin-like ligase-substrate adaptor activity
Biological process: negative regulation of protein ubiquitination; response to virus; RNA splicing; proteasome-mediated ubiquitin-dependent protein catabolic process; transcription by RNA polymerase III
Cellular component: cytosol; Cul3-RING ubiquitin ligase complex; cytoplasm; spliceosomal complex; transcription regulator complex; cytoskeleton; nucleoplasm; nucleus
Genetic constraint (gnomAD): Loss-of-function variants: 24 observed, 74.46 expected, observed/expected ratio (o/e) 0.32, 90% interval 0.23 to 0.45. The upper end of that interval is the gene's LOEUF score, 0.45, which puts it in group 2 of 6, group 1 being the genes least tolerant of losing a copy. Missense variants: 469 observed, 752.62 expected, observed/expected ratio (o/e) 0.62, 90% interval 0.58 to 0.67. Synonymous variants: 222 observed, 257.45 expected, observed/expected ratio (o/e) 0.86, 90% interval 0.77 to 0.96.
Homologues: Orthologues: chimpanzee IVNS1ABP (100% identical), macaque IVNS1ABP (99% identical), rat Ivns1abp (98% identical), guinea pig IVNS1ABP (97% identical), mouse Ivns1abp (97% identical), pig IVNS1ABP (96% identical), dog IVNS1ABP (95% identical), rabbit IVNS1ABP (90% identical), tropical clawed frog ivns1abp (78% identical), zebrafish ivns1abpa (78% identical), zebrafish ivns1abpb (74% identical). Paralogues in human: KLHL20 (29% identical), KLHL17 (27% identical), KLHL3 (27% identical), KLHL2 (27% identical), KLHL5 (26% identical), KLHL1 (25% identical), KLHL4 (25% identical), KEAP1 (25% identical), KLHL12 (25% identical), KLHL28 (24% identical), KLHL24 (23% identical), KLHL10 (23% identical), and 42 more.
Diseases named in the same sentence as IVNS1ABP in open-access papers:
IVNS1ABP is named in the same sentence as 12 diseases in open-access papers, as found by Europe PMC text mining. Sharing a sentence is not in itself a finding about the gene and the disease. The quoted sentences say what the papers report.
viral infection (2 papers, 2014 to 2016). "Among the differential ASEs associated with viral infection, at least 10 ASEs resulted in the addition or loss of predicted nuclear localization signals (NLS) including the CDC-Like Kinase 4 (CLK4), the e2F3 transcription factor, and the Influenza Virus NS1A Binding Protein (IVNS1ABP)." (PMID 27598998, 2016).
endometrioid carcinomas (1 paper, 2024). "Eight common proteins were identified between normal endometrium with diploid endometrioid carcinomas and diploid with aneuploid endometrioid carcinomas, namely ACTB, ATP5B, ATP5E, INS, IVNS1ABP, LMNB, PLS1, and VIM." (PMID 39194522, 2024).
liver cancer (1 paper, 2023). An epithelial or non-epithelial malignant neoplasm that arises from the liver. "Most importantly, proteomic analyses determined that CCDC9B loss impaired protein levels of its partner, the MYC-regulator Influenza Virus NS1A Binding Protein (IVNS1ABP), creating sensitivity to bromodomain inhibitors in liver cancer cells exhibiting NSUN7 epigenetic silencing." (PMID 37173708, 2023).
Obesity (1 paper, 2010). Accumulation of substantial excess body fat. "An interesting candidate for obesity is IVNS1ABP (influenza virus NS1A binding protein)." (PMID 20532202, 2010). "While it has no known function with a relation to obesity, a recent study of Oceanian population genetics utilizing genome-wide SNP analyses identified the IVNS1ABP gene as having undergone a selective sweep in the Oceanian population." (PMID 20532202, 2010).
tumor (4 papers, 2016 to 2020). "Expression of the miR203 target genes, STAT1, PI3KCA and IVNS1ABP, was markedly inhibited in tumor extracts from mice injected with enforced miR203 expressing cells as determined by qPCR, and immunoblotting." (PMID 27705947, 2016). "Moreover, circDUSP16 possessed a co-localization with miR-145-5p in the cytoplasm, and acted as a sponge of miR-145-5p, which attenuated circDUSP16-induced tumor-promoting effects and IVNS1ABP expression in GC cells." (PMID 31776711, 2020). "Tumor tissue from mice injected with GBM cells with enforced miR203 expression had lower protein levels of miR203 targets (STAT1, PI3KCA and IVNS1ABP), but the levels of STAT3 and actin were unaffected." (PMID 27705947, 2016).
cancer (2 papers, 2018 to 2023). A tumor composed of atypical neoplastic, often pleomorphic cells that invade other tissues. "Interestingly with regard to cancer biology and for therapy-related facets, a role for IVNS1ABP in MYC-associated pathways has been reported and a certain degree of association between sensitivity to bromodomain inhibitors and enhanced MYC-signaling has also been described." (PMID 37173708, 2023).
IVNS1ABP also shares sentences with these, for which no sentence is quoted: infection (4 papers); colon cancer (2); esophageal squamous cell carcinoma (2); malaria (1); Neurological Disorder (1); type 2 diabetes (1).